AFP (alpha fetoprotein)
Diseases named in the same sentence as AFP in open-access papers (continued):
Sharing a sentence is not in itself a finding about the gene and the disease.
Cirrhosis (continued). "Results of HCC without cirrhosis including both markers revealed a better AUC for AFP (0.828) as compared to sAxl (0.804) alone, but sAxl showed higher sensitivity (60.7%) and specificity (96.4%) than AFP alone (sensitivity: 53.6%; specificity 100%)." (PMID 28526812, 2017). "Surveillance screening with regular ultrasounds (every 6 months) with or without use of serum alpha fetoprotein should be undertaken as is the case in HIV-negative individuals with cirrhosis." (PMID 27471521, 2016). "In this study, we investigated CCT3 and IQGAP3 at plasma levels in patients with HCC or cirrhosis and in healthy individuals, and evaluated their application in detecting small and AFP-negative tumors in patients with HCC." (PMID 27390551, 2016). "In the first one, 18,816 patients with chronic hepatitis B infection regardless of cirrhosis status underwent US investigation and determination of the tumor marker alpha-fetoprotein (AFP) every six months and were compared to patients without any screening." (PMID 26854167, 2015). "These include the presence or absence of cirrhosis in the non-neoplastic liver, tumor multifocality, pre-surgery AFP, Child-Pugh class status, vascular invasion, tumor size, margin distance and the presence or absence of symptoms at diagnosis." (PMID 25830231, 2015). "Sex, age, hepatitis B virus infection background, AFP, cirrhosis, Child-Pugh score, and tumor size had no prognostic significance for OS and TTR." (PMID 25609201, 2015). "And AFP serum levels have no prognostic meaning in well-compensated cirrhosis patients with single, small HCC treated with curative intent." (PMID 25165471, 2014). "Elevated AFP levels are also found in patients with chronic viral hepatitis and cirrhosis without HCC." (PMID 27335844, 2014). "Some patients with cirrhosis or hepatic inflammation have an elevated level of AFP without the presence of tumors." (PMID 25165471, 2014). "Hepatic cirrhosis was associated with a higher aspartate aminotransferase/platelet ratio index (APRI), no fatty change of the liver, higher BMI and higher AFP levels." (PMID 24349054, 2013). "We used a comparative analysis of patients with and without cirrhosis and identified a combination of 4 variables (AFP, PT, PLT and CP) that we used in our predictive model, APPCI." (PMID 24282481, 2013). "Patients with CC usually have no cirrhosis and do not develop choloplania, and their levels of AFP are normal." (PMID 23326418, 2013). "Expression of PDGFR-β correlated with AFP level, tumor number, and cirrhosis, but did not correlate with gender, age, HBsAg status, tumor size, degree of tumor differentiation, Child-Pugh class, BCLC stage, ascites, tumor thrombus, or extrahepatic metastasis." (PMID 23552472, 2013). "In case of marked alterations of these indices, even in the absence of cirrhosis, alpha-fetoprotein levels measurement and hepatic ultrasound examination should be implemented." (PMID 23162599, 2012). "In contrast, AFP, when analyzed in this cohort, had an AUROC of 0.764 and could differentiate HCC from cirrhosis with a sensitivity of 59% and a specificity of 93% using a cut-off of 20 ng/mL." (PMID 20811639, 2010). "A study in Japan of 1377 HCC patients and 355 non-HCC controls with chronic hepatitis or cirrhosis showed that the utility of DCP for the diagnosis of HCC was lower than that of AFP for small tumors, but higher than that of AFP for large tumors." (PMID 21092242, 2010). "We report a case of 45 year old female with inactive hepatitis B virus (HBV) carrier status and persistently elevated alpha-fetoprotein (AFP), presented with features of portal hypertension and without evidence of cirrhosis or fibrosis on liver biopsy." (PMID 18842148, 2008).
Cirrhosis (continued). "Important relevant data include serum alpha-fetoprotein (AFP) and carcinoembryonic antigen (CEA) levels, hepatitis virus markers, results of liver function tests, presence of cirrhosis, biliary tract disease, calculi, liver fluke infestation, and history of hormone usage." (PMID 15941489, 2005). "We also explored the relationship between CREB5 expression and the clinicopathological features of HCC, finding that high CREB5 expression was correlated with tumor size and degree of differentiation, but not with age, sex, history of hepatitis/cirrhosis, or AFP level." (PMID 39915455, 2025). "This consistent high performance across internal and external validation underscores the potential of miR-200a-3p, not as a standalone test, but as a synergistic enhancer of AFP, for non-invasive identification of HCC in high-risk patients with underlying CHB or cirrhosis." (PMID 41459517, 2025). "Moreover, AFP elevations are not specific to malignancy, as they are frequently observed in benign liver conditions such as cirrhosis and chronic hepatitis." (PMID 41002319, 2025). "In addition, not all HCC cases produce AFP, and its levels can also be elevated in cirrhosis or hepatitis." (PMID 40038575, 2025). "In addition, although AFP is not included in non‐invasive indexes, it had a remarkable contribution in predicting cirrhosis." (PMID 40384539, 2025). "Current recommendations for HCC screening, as endorsed by professional society guidelines, include semi-annual abdominal ultrasound with or without serum alpha-fetoprotein (AFP) for patients with cirrhosis and subgroups with chronic hepatitis B virus infection." (PMID 39744233, 2025). "In addition, BMI (P = 0.034), cirrhosis (P = 0.00), and some laboratory indexes, such as ALT (P = 0.044), TBIL (P = 0.000), and PLT (P = 0.004), indicating liver function estimation and AFP (P = 0.000), were significantly difference between the HCC group and the non-HCC group." (PMID 38515017, 2024). "We were unable to assess the impact of surveillance, but 6-monthly liver ultrasounds, with or without serum alpha-fetoprotein testing, have been shown to improve early detection, receipt of curative treatment and survival and is therefore recommended for people with cirrhosis." (PMID 38499728, 2024). "Primary cirrhosis etiology was mostly hepatitis C virus (57%, 181/316), with 69% (217/316) of patients having Child Pugh A. The median index lesion size was 2.8 cm, with 93% (294/316) having HCC staging of BCLC A and median alpha fetoprotein (AFP) levels of 13.2 ng/mL." (PMID 38201639, 2024). "However, approximately 30% of patients with early-stage HCC are AFP negative, and elevated AFP levels are also detected in patients with cirrhosis or chronic HCV exacerbations." (PMID 38561745, 2024). "Furthermore, patients with cirrhosis and HCC had higher levels of both AAT and kininogen than those with cirrhosis alone, and combining kininogen and AAT with AFP and Golgi protein 73 resulted in an increased sensitivity of 95%, a specificity of 70%, and AUROC of 0.94 for the detection of HCC." (PMID 37759769, 2023). "However, the TPS model did not seem to show superiority in predicting early recurrence in the subgroup of AFP‐negative HCC patients with cirrhosis after liver resection." (PMID 38130028, 2023). "Although AFP has historically been plagued by low specificity in the setting of active viral hepatitis, most recent data suggest this is less of a problem in nonviral etiologies of cirrhosis." (PMID 37144952, 2023). "Thus, the ability of predicting early recurrence in the AFP‐negative HCC patients after liver resection with cirrhosis needs to be further studied although the TPS model is not inferior to traditional stage systems (BCLC and AJCC TNM stage)." (PMID 38130028, 2023). "It has also been reported that the AFP level might be falsely elevated in patients with chronic hepatitis or cirrhosis without HCC." (PMID 37920152, 2023).
Cirrhosis (continued). "AFP elevation is absent in a significant portion of tumors, and imaging may have low sensitivity for smaller tumors or in the presence of cirrhosis." (PMID 37445822, 2023). "The low DDX60L expression in HCC patients with no-metastasis, age ≥55 years, tumor size <5 cm, Edmondson grade = I–II, microvascular invasion, no cirrhosis, HBV positivity, tumor stage = III–IV, AFP >20 μg/L, and multiple tumor was associated with poorer prognosis (P <0.05)." (PMID 35223465, 2022). "Furthermore, AFP levels can be elevated in patients with nonspecific conditions like cirrhosis or chronic HCV exacerbations." (PMID 36079006, 2022). "Cao found that variations in PON1 glycosylation may help to distinguish AFP negative HCC from cirrhosis." (PMID 35126478, 2022). "Compared with miRNAs and AFP in plasma, exosomal miRNAs showed significantly higher accuracy in discriminating the HCC group from the healthy group (p < 0.001 for miRNA-26a, miRNA-29c, and miRNA-199a) and hepatic cirrhosis group (p < 0.001 for miRNA-26a, miRNA-29c, and miRNA-199a)." (PMID 36211468, 2022). "Within our study, we observed that, in patients with decompensated cirrhosis, where the mean HCC size was 5.8 cm (maximum tumour diameter ranging between 3.3 and 8.2 cm), AFP levels were mostly over 300 ng/ml, with many values exceeding 500 ng/ml and with a mean AFP of 660 ng/ml." (PMID 35497085, 2022). "Several patients with hepatic inflammation and/or cirrhosis may have an increased AFP without the existence of the tumor." (PMID 35547447, 2022). "Similarly, exosomal circ0070396 is superior to AFP in distinguishing HCC patients from healthy persons and can also be used to distinguish liver cancer patients from patients with chronic hepatitis B and patients with cirrhosis." (PMID 35126514, 2022). "Serum AFP could be falsely elevated in patients with chronic active hepatitis, advanced fibrosis, and cirrhosis but without evidence of HCC." (PMID 36016291, 2022). "In addition, the reactivity of PON1 with LCA in HCC patients with negative AFP was significantly elevated than that in cirrhosis patients." (PMID 33889548, 2021). "However, not all HCC tumors secrete AFP, while it can also be elevated in cases of hepatitis or cirrhosis." (PMID 34145988, 2021). "Variations in PON1 glycosylation may be associated with AFP-negative HCC and might be helpful to serve as potential glycomic-based biomarkers to distinguish AFP-negative HCC from cirrhosis." (PMID 33889548, 2021). "Among patients treated with preferred DAAs, cirrhosis, HBV coinfection, BMI ≥25, HbA1c ≥ 6.5, HOMA index ≥2, triglyceride ≥150 mg/dl, the use of sofosbuvir-based or EBR/GZR regimens, pre-therapy ALT ≥1xULN, higher AST, AFP, T-Bil, and lower albumin level was found." (PMID 34566631, 2021). "Moreover, hsa_circ_0028861 also exhibited good diagnostic performance with an AUC of 0.78 in discriminating AFP (−) HCC patients from the combination of chronic HBV and cirrhosis patients, and the corresponding sensitivity and specificity was 71.43 and 80.77%, respectively." (PMID 34367259, 2021). "Unlike AFP, the sialylated N-glycopeptides decreased in abundance from cirrhosis to HCC." (PMID 34436504, 2021). "However, AFP levels also increase in non-malignant hepatic diseases such as acute/chronic hepatitis and cirrhosis, or in normal pregnancy." (PMID 33913027, 2021). "First, all of the patients enrolled in our study, including those without underlying advanced fibrosis or cirrhosis, underwent a routine biannual HCC surveillance based upon abdominal ultrasonography and serum alpha-fetoprotein during antiviral treatment and the follow-up after SVR." (PMID 33217965, 2020). "However, other factors such as age, sex, hepatitis B, cirrhosis, Child-Pugh grading, tumor differentiation, pre-LT serum AFP level, and antineoplastic prophylaxis after LT failed to influence patient recurrence events (P > 0.05)." (PMID 32226523, 2020).
Cirrhosis (continued). "Interestingly and importantly, our findings firstly suggest Sphingosine (d18:1)-1-P can effectively discriminate AFP-negative HCC from cirrhosis." (PMID 33014866, 2020). "Interestingly, AFP of HBeAg‐ HBV‐HCC patients without cirrhosis was significantly higher than that of the HBeAg+ patients." (PMID 32150664, 2020). "Spearman rank correlation analysis revealed that the level of serum Sphingosine (d18:1)-1-P was not correlated with AFP in cirrhosis (r = −0.04, P = 0.71), total HCC (r = 0.06, P = 0.60), AFP-positive HCC (r = −0.09, P = 0.56), or AFP-negative HCC (r = −0.13, P = 0.55), respectively." (PMID 33014866, 2020). "Studies have found that compared with AFP-positive HCC patients, AFP-negative HCC patients were less likely to feature cirrhosis nodules and poor Edmondson–Steiner grade; conversely, they are more likely to form complete tumor capsules and have a favorable long-term prognosis." (PMID 33014866, 2020). "However, the abnormally elevated serum AFP level was also found in patients with chronic hepatitis B or cirrhosis without evidence of HCC." (PMID 33490235, 2020). "Moreover, in view of the etiology heterogeneity and different ethnics, further screening sphingolipid metabolites which can distinguish HCC (including AFP-negative HCC) from cirrhosis with high sensitivity and specificity is imperative." (PMID 33014866, 2020). "In addition to 1.2‐fold increasing AFP in HBV patients with cirrhosis compare to CHB patients without cirrhosis (P < .05), the level of AFP in HBV‐HCC patients with antiviral therapy was ~60% lower than those in the patients without no‐antiviral (P < .05)." (PMID 32150664, 2020). "Combination of AFP with ALT, AST, and NLR improved the diagnostic performance for HBV‐HCC, compared to any of the single biomarkers or any other combinations among these patients (except no‐cirrhosis)." (PMID 32150664, 2020). "Significant variables between the two groups included race, AFP level, and no cirrhosis/cirrhosis." (PMID 32913474, 2020). "However, owing to increased AFP levels in patients with hepatitis and cirrhosis, not all patients with HCC show high levels of AFP, and approximately 40% of patients with HCC have negative AFP20." (PMID 32782270, 2020). "However, the presence of cirrhosis did not affect the characteristics of the tumor itself, such as AFP." (PMID 30886700, 2019). "Neither AFP nor cirrhosis status were found to be significant." (PMID 30833661, 2019). "However, log10 AFP (p= 0.204, OR = 1.74, 95% CI: 0.74 - 4.06) revealed non-significant contribution of AFP measurement indicating superiority of miRNA-215 over AFP regarding HCC prediction versus cirrhosis." (PMID 31554369, 2019). "Primary hepatic neuroendocrine carcinoma should be considered when no hepatitis or cirrhosis has been diagnosed, AFP is not high, imaging findings suggest solid occupying lesions, liquefaction, and clear boundaries of liver tumors, and other primary lesions have not been found." (PMID 30416612, 2018). "However, AFP is also elevated in the patients with non-cancerous liver disease such as hepatitis or cirrhosis, and AFP is also produced and released from injured liver tissue or other tissues." (PMID 30065664, 2018). "Accuracy of commonly used blood markers, alpha-fetoprotein (AFP) or des-gamma-carboxy prothrombin is modest, with false negative results in one-third of cases of HCC and a high rate of false positive results in patients with benign liver diseases, such as hepatitis and cirrhosis." (PMID 29632649, 2018). "The TT variant of rs3830041 was associated with increased death risk in the following subgroups: age ≤45 years, nonsmoking status, AFP >400 ng/ml, cirrhosis, PVTT, antiviral therapy, nonadjuvant TACE, nonradical resection, nonregional invasion, nonintrahepatic metastasis, and vascular invasion." (PMID 28568708, 2017).
Cirrhosis (continued). "However, it seemed that both AFP and PIVKA-II could hardly differentiate early-stage HCC from cirrhosis, though the AUROC for AFP (0.635, 0.595–0.674) was slightly better than PIVKA-II (0.607, 0.566–0.646)." (PMID 28863782, 2017). "Interestingly, the other conventional clinicopathological parameters, such as gender (P=0.81), age (P=0.99), AFP (P=0.24), HBsAg (P=0.85), ALT (P=0.72), Cirrhosis (P=0.40), tumor size (P=0.65, all done by chi-square test), none of them was significantly correlated with AGGF1 expression." (PMID 29340079, 2017). "Likewise, the range of AFP values in HCC is quite wide, from normal concentrations to >100,000 ng/mL, and non-cancer liver diseases such as chronic hepatitis or cirrhosis are associated with increased AFP levels." (PMID 30159431, 2017). "However, surveillance with USG and AFP becomes cost-effective once the incidence of HCC exceeds 0.2 %/year in hepatitis B infected subjects without cirrhosis." (PMID 26563120, 2016). "However, high JARID2 expression in HCC tissues did not correlate with gender, age, HBV infection, AFP, presence of cirrhosis, size of the tumor and presence of encapsulation." (PMID 27259236, 2016). "Furthermore, male, older age, cirrhosis, non-SVR, and alpha-fetoprotein (AFP) level were reported to be associated with the development of HCC." (PMID 26913058, 2016). "Currently, alpha-fetoprotein (AFP) is used as a standard serum marker for the detection of HCC, but its sensitivity and specificity are unsatisfactory, and optimal diagnostic markers for cirrhosis are lacking." (PMID 25996938, 2015). "In addition, AFP concentrations are raised in 11–58% of patients with chronic hepatitis or cirrhosis in the absence of HCC, which was supported by our results." (PMID 25871387, 2015). "However almost all serological data concerning GP73 and AFP in patients with HCC used patients with cirrhosis, hepatitis or no liver disease as controls." (PMID 25033446, 2014). "Patients usually deny histories of hepatitis or cirrhosis and exhibit AFP-negative serum levels." (PMID 24944650, 2014). "Additionally, hepatic cirrhosis was also associated with higher APRI, no fatty change of the liver, higher BMI and higher AFP levels." (PMID 24349054, 2013). "Expression of VEGFR-2 correlated with gender, HBsAg status, degree of tumor differentiation, and hepatic cirrhosis, but did not correlate with age, AFP level, tumor number, tumor size, Child-Pugh class, BCLC stage, ascites, tumor thrombus, or extrahepatic metastasis." (PMID 23552472, 2013). "However, an increase of AFP is not always pathognomonic for liver cancer, as elevated AFP levels can be found in end-stage liver disease (cirrhosis) unrelated to tumor development." (PMID 23710207, 2013). "Although no definitive answer can be provided here, one possible interpretation, might be related to the fact that non-significant AFP elevation will occur when either hepatitis reactivation or change of cirrhosis status will occur after radiotherapy." (PMID 23216929, 2012). "Some patients with cirrhosis and/or hepatic inflammation could have an elevated level of AFP without the presence of tumors." (PMID 22244200, 2012). "-AFP was better than MDK in distinguishing HCC from non-HCC cases and HCV or HBV-associated HCC from liver cirrhosis.-MDK could distinguish NASH-related HCC from cirrhosis. -MDK was elevated 6 months prior to diagnosis in 67% of patients." (PMID 38247828, 2024). "With reported surveillance compliance, test performance, and prevalence of cirrhosis and viral hepatitis in China, Monte–Carlo simulation revealed that HepaAiQ could lead to a 2.5‐fold (95% CI: 1.8–3.4) increase in HCC detection compared to ultrasonography combined with AFP." (PMID 38741204, 2024).